IL13 (interleukin 13)
Diseases named in the same sentence as IL13 in open-access papers (continued):
Sharing a sentence is not in itself a finding about the gene and the disease.
tumor (continued). "As MF progresses, there is a decline in anti-tumor Th1 responses (e.g., IFN-γ, IL-12) and a predominance of Th2 cytokines such as IL-4, IL-5, and IL-13." (PMID 40864740, 2025). "Further, when stratified SCC patients according to α3 Laminin expression it has been demonstrated that lower α3 Laminin expression confers tumor cells a more invasive behavior and that these cells release higher amount of CCL-2/MCP-1 and IL-13." (PMID 40868818, 2025). "Cytokines, such as CCL-2, IL-6, IL-8, IL-10, IL-13, and TNF-α, exhibit tumor-specific secretion profiles." (PMID 40777043, 2025). "Various cytokines produced by both tumor and stromal cells, such as GM-CSF, M-CSF, VEGF, IFN-γ, IL-4, IL-6, IL-13, and TGF-β, are involved in MDSC activation through STAT3 pathways." (PMID 40805183, 2025). "In contrast, M2 polarization is driven by interleukin-4 (IL-4), interleukin-13 (IL-13), macrophage colony-stimulating factor (M-CSF), and transforming growth factor-β (TGF-β), contributing to pro-tumor characteristics." (PMID 40547026, 2025). "IL-13, which is known to promoting the Th-2 phenotype in both malignant CTCL cells and non-malignant T cells, along with IL-5, plays a crucial role in tumor progression." (PMID 41221277, 2025). "CD4+ T cell subsets, particularly Th2 and Th17, contribute to tumor progression by promoting TAM and MDSC recruitment via IL-4, IL-13, and IL-17-driven pathways." (PMID 40475782, 2025). "Their functional maturation is promoted by cytokines such as IL4, IL6, IL13, and TNF, while mobilization into the tumor niche is orchestrated by chemoattractants including IL8, CCL2, and CXCL12." (PMID 41155172, 2025). "Research has demonstrated that Th2 cells exert pro-tumor role through the release of tumor-supporting factors IL4 and IL13." (PMID 40369667, 2025). "Additional DE and PTM overlapping pathways, including HMGB1 signaling, the regulation of the epithelial–mesenchymal transition (EMT) by growth factors, and IL-4 and IL-13 signaling, indicated the broader impact of RONS on the tumor microenvironment." (PMID 39857768, 2025). "IL-13-LCL-SIM selectively depleted protumoral M2-TAMs, while PEG-EV-DOX delivered doxorubicin (DOX) to tumor cells, inducing oxidative stress and apoptosis." (PMID 40861441, 2025). "Cytokines including CCL-2, IL-6, IL-8, IL-10, IL-13, and TNF-α show tumor-specific secretion profiles, with experimental evidence demonstrating TIC-derived cytokines mediate immune evasion through recruitment and activation of MDSCs and TAMs." (PMID 40777043, 2025). "M2 expresses high levels of CD163, CD206, CCL18, and CCL22, releasing anti-inflammatory (TGF-β, IL-4, and IL-13) and inflammatory (IL-6, IL-12, and TNF-α) factors, as well as tumor-promoting arginase-1 and VEGF, modulated by TME signals." (PMID 40940877, 2025). "To understand if IL-13 producing CD49a+CD103+ ieILC1-like NK cells have physiologic relevance, we looked in cultures of tumor infiltrating lymphocytes (TIL) from primary tumors for their presence." (PMID 40114916, 2025). "Furthermore, cytokines secreted by TH2 cells, including IL-4 and IL-13, stimulate lung mesenchymal stromal cells to upregulate C3 expression, which promotes neutrophil recruitment and the formation of extracellular traps, ultimately contributing to tumor metastasis." (PMID 40260250, 2025). "GSEA using Reactome terms identified increased interleukin activity of tumor-infiltrating DCs with IL4, IL13, and IL10 predicted to elicit the greatest impact on infiltrating DCs." (PMID 39932553, 2025). "These activated mast cells, in turn, induce tumor proliferation and modify the tumor microenvironment by secreting factors such as PDGF, CD73, and IL-13." (PMID 39814702, 2025). "Targeting interleukin (IL)-33, IL-13, and ILC2 activation suppressed metaplasia and tumor progression in APP mice." (PMID 40761291, 2025).
tumor (continued). "Upon release by both tumor and stromal cells, IL-33 activates ILC2s through its receptor, ST2, leading to the production of cytokines such as IL-5 and IL-13." (PMID 40247153, 2025). "The Th2-dominant tumor microenvironment (TME) in MF features elevated IL-4 and IL-13, which promote malignant T cell survival and suppress cytotoxic responses." (PMID 40864740, 2025). "TH2 cells secrete IL4, IL5, IL10, IL13, and IL17 - all of which have been shown to contribute to the tumor-promoting role of this subtype, even though IL4, IL5, and IL13 have been shown to contribute to the growth and metastasis of cancer." (PMID 41019045, 2025). "Previous studies have mainly explored the biological function of M2-type macrophages driven by IL‐4 or IL‐13, and macrophages undergoing LAP also exhibit a tumour-promoting phenotype." (PMID 39756316, 2024). "The study also revealed that significant cell death can trigger cytokines like IL‐4, IL‐10, IL‐13, and TGF‐β, which aid in efferocytosis‐induced wound healing and further support the progression of metastatic tumours." (PMID 38501838, 2024). "Pro-tumour cytokines such as vascular-endothelial growth factor α (VEGF-α) and the interleukins (IL) IL-4, IL-5, IL-6, IL-10, and IL-13 produced by T-helper (Th2) lymphocytes have also been linked to the pathogenesis of MCD." (PMID 40729293, 2024). "Among them, M2a is induced by IL-4/IL-13 and secretes IL1-Ra, arginase-1 (Arg-1), TGF-β, CCL17, and CCL18, which inhibit M1-TAM polarization and promote tumor cell growth and metastasis." (PMID 39560523, 2024). "TAMs secrete a series of cytokines and inflammatory factors such as TGF-β), IL-6, IL-10, IL-13, IL-4 and TNF-α that promote tumour initiation, growth, metastasis, angiogenesis, proliferation and chemoresistance in HCC (Ref." (PMID 39320855, 2024). "CSCs release galectin-3, growth differentiation factor 15 (GDF-15), interleukin-10 (IL-10), interleukin-13 (IL-13), prostaglandin E2 (PGE2), and transforming growth factor-beta (TGF-β), which are known to modulate the tumor niche." (PMID 38920716, 2024). "High Il33 expression in tumor cells recruits and activates TH2 and ILC2 cells which secrete pro-tumorigenic cytokines such as Il4, Il5, and Il13." (PMID 38942797, 2024). "The molecular link between these cell subsets appears to be IL-13, as M-MDSCs recruited to the bladder highly express IL-13Rα1, and ILC2s secrete IL-13 in response to BCG and tumor cells in vitro." (PMID 38667314, 2024). "M2 macrophages secrete anti-inflammatory cytokines, such as IL-6, IL-10, IL-13, TGF-β, and chemokines and proteases, such as Arginase1, MMP, and VEGF-A, which promote tumor growth, angiogenesis, and metastasis." (PMID 35895109, 2023). "For example, studies have suggested that tumor-promoting Th2 cells have high levels of IL-10 and TGF-β, whereas Th2 cells with high expression of IL-3, IL-5, IL-13, and GM-CSF exhibit pro-inflammatory and anti-tumor immunity." (PMID 37332039, 2023). "This analysis revealed that while in the heart of PyMT-bearing mice, INFγ and TNFα are at low levels; IL-13 and CCL2 are elevated in the PyMT tumor." (PMID 37508517, 2023). "Macrophages are classified into tumor-suppressive M1 type (activated by interferon-γ (IFN-γ) stimulation) and tumor-promoting M2 type (activated by IL-4 and IL-13 stimulation) according to the type of stimulation from their environment." (PMID 37370118, 2023). "TAMs and other tumor-promoting cells in TME can also facilitate the polarization of monocytes toward TAMs by releasing IL-4, IL-10, IL-13, and TGF-β." (PMID 37221555, 2023). "The accumulation of TAMs following interactions with CAFs can exhaust the anti-tumor function of NK and CD8 + T cells by secreting TGF-β, COX-2, PGE2, IL-10, IL-4, IL-13, and some others." (PMID 37221555, 2023).
tumor (continued). "We next determined the effect of Q11 on the secretion of tumor‐promoting inflammatory cytokine, and found that the TGF‐β level in the conditioned medium was significantly increased in the IL‐4/IL‐13 induced group but decreased upon Q11 treatment." (PMID 37875398, 2023). "Tumor-derived GM-CSF, IL-6, IL-1β, TGF-β, IL-13, IFN-γ, CXCL5 have also been found to regulate MDSC accumulation and the polarization of tumor-infiltrating granulocytic MDSC (G-MDSC) toward an immunosuppressive phenotype." (PMID 38304256, 2023). "Analysis of keywords like “interleukin-13,” “TGF-beta,” and “dendritic cells” indicated progression from foundational cytokine therapies to sophisticated understanding of the tumor microenvironment and immune dynamics." (PMID 38259287, 2023). "Four of these cytokines (MCP-3/CCL7, PDGF-AB/BB, IL-13, and IL-3) showed significance in all analyses performed in our study (CMs vs. controls, GEP Class 2 vs. Class 1 CMs, and correlations with tumor dimensions)." (PMID 37509362, 2023). "Type II NKT cells upregulate IL-13 expression to inhibit CTL-mediated tumor immune surveillance and tumor-specific CD8+ T cells, which are involved in cancer progression." (PMID 37857728, 2023). "In contrast, the production of immune checkpoint molecules like PD-1 and the cytokines IL-4 and IL-13 dampens ILC2 activity and accelerates tumor growth." (PMID 37510993, 2023). "IL-4 and IL-13 are produced by several cell types including eosinophils, basophils, mast cells, NKT cells, ILC2 cells, macrophages, Th2 cells, and tumor cells." (PMID 37108657, 2023). "In the context of cancer, the type 2 cytokines IL-4, IL-5, IL-9, and IL-13 along with ILC2s, Th2, and Th9 cells may either promote or inhibit tumorigenesis in a context-dependent manner that involves complex interactions with cancer cells and the constituents of the tumour microenvironment." (PMID 37455828, 2023). "In cHL, HRS cells can lead TAMs to polarize towards the tumor-promoting M2 phenotype via the secretion of TGF-β and IL-13." (PMID 37372147, 2023). "In immune‐intact mice CDXs, apart from inhibiting tumor growth, ANO1 knockdown also increased the anti‐tumor immune activity, marked by increased infiltration/expression of CD8+ T cells/IFN‐γ/TNF‐α/granzyme B/IL‐13 and reduced PD‐L1 expression." (PMID 37341301, 2023). "Activated macrophages are classified into anti-tumor M1 and pro-tumor M2 types by the action of cytokines such as TGF-β1, IL-4, and IL-13." (PMID 37161430, 2023). "Th2 cells are also important tumor-promoting cells that can promote the M2 polarization of macrophage by secreting IL4 and IL13 cytokines." (PMID 37610668, 2023). "Enhanced anti-tumor activity and T cell persistence in patients with IL13BB-CAR-T cells as compared to first-generation IL13-CAR CD8+ indicates the biological activity of T cells." (PMID 37304305, 2023). "To further evaluate the safety of IL13-BBζ CAR T cells, we developed a fully murine IL13(E12Y)-CAR to better assess off-tumor toxicities in immunocompetent mouse models of GBM, and administered the CAR T cells systemically with and without lymphodepletion." (PMID 36968221, 2023). "CSCs can recruit immunosuppressive properties of DCs by producing immunosuppressive cytokines, including IL-13, IL-10, IL-4, and co-inhibitory molecules like B7-H3, IDO1 and PD-L1 which induce tumor properties of DCs." (PMID 36207500, 2022). "Our data clearly showed that among the monotherapies, IL-13-conjugated LCL-SIM and PEG-EV-DOX elicited the strongest reduction in tumor volume." (PMID 35450036, 2022). "IL13-PE treatment of orthotopic GBM and pancreatic xenografts significantly reduced tumor burden and increased overall survival." (PMID 35464460, 2022). "When the TME becomes more pro-tumor, IL4, IL13, or IL10, produced by Th2 or Treg cells, promote M2 or M2-like phenotype for TAM, displaying protumor functions." (PMID 35163420, 2022).
tumor (continued). "Based on previous studies, we concluded that the tumor microenvironment, HDAC6, and IL-13 play a very important role in the carcinogenesis of OSCC." (PMID 35732647, 2022). "The secreted IL-33 recruited and activated Th2 and innate lymphoid cells 2 (ILC2) in the tumor microenvironment (TME), which stimulated tumor growth by secreting pro-tumor cytokines, such as IL-4, IL-5, and IL-13." (PMID 35910636, 2022). "IL-4 and IL-13 have both been shown to supress the anti-tumoural immune response, and moreover to directly drive the proliferation of KRAS-mutant tumour cells." (PMID 36010845, 2022). "After 15 min incubation with the liposomal formulations, the superior binding capacity of IL-13-LCL to M2 macrophages compared to M1 macrophages and tumor cells was reported (p < 0.05)." (PMID 35450036, 2022). "In summary, CSCs release a variety of immunosuppressive cytokines and chemotactic factors such as; PGE2, IL-10, TGF-β, IL-4, IL-13 and IL-35 that affect different immune cells in the TME and promote tumor invasion and progression." (PMID 36207500, 2022). "ILC2 secrete IL-13, which promotes the aggregation of MDSC and inhibits the anti-tumor response of CTL." (PMID 35874717, 2022). "On the other hand, cytokines such as IL-4, IL-13, and MYC influence the development of “alternative” M2 macrophages, having pro-tumor activity, with angiogenesis induction." (PMID 36294305, 2022). "Tregs are notorious for inhibiting anti-tumor responses by penetrating the tumor microenvironment and releasing inhibitory cytokines (TGF-β, IL-13, IL-35), disrupting immune checkpoint-related pathways, and preventing antigen-presenting cell (APC) maturation." (PMID 35806311, 2022). "Moreover, the secretion of IL-13, IL-34 and osteoactivin by CCA tumor spheres is implicated in the macrophage acquisition of a CSC-specific phenotype characterized by the concomitant expression of M1 and M2 transcription traits and the presence of tumor-promoting functions." (PMID 36612000, 2022). "In spleen cell supernatants, IFN-γ, IL-4, IL-1β, IL-6, IL-13, MCP-1, and IL-21 were significantly higher in the tumour-bearing SID animals compared to the healthy controls." (PMID 36010845, 2022). "The activated mast cells also produce IL1β, IL6, IL8, IL13, TGFβ, TNFα, PDGF, and VEGF for promoting tumor growth and metastasis directly, and also indirectly by provoking angiogenesis and immune chaos." (PMID 36211375, 2022). "In a dual targeting approach aimed at superior targeting ability and delivery to tumor neovasculature and tumor cells, PEG-PCL nanoparticles were functionalized with RGD peptide and interleukin-13 peptide." (PMID 34959326, 2021). "In the study, IL13-zetakine CAR T cells were administered via an implanted reservoir/catheter system and led to treatment-induced inflammation at the tumor site." (PMID 34298615, 2021). "Among the cytokines that correlate with CD68+ macrophages, IL-1β, IL-13 and VEGF have previously been described as tumor promoting factors." (PMID 34654395, 2021). "We and others have found that BI-ALCL tumor cells exhibit an activated CD4+ transcriptional profile with T regulatory features due to an IL10-, IL6-, IL13- and Eotaxin-rich cytokine microenvironment." (PMID 34944796, 2021). "The receptor for IL-13 is abundantly expressed in CRC tumours and precancerous polyps, and can act as a pro-tumour factor." (PMID 33808058, 2021). "Each CD44+ cell-type functions immunosuppression through different ways: CD44+ tumor cells express CD276, IL13, VEGFA, and IDO1; CD44+ TAMs express IL10, TGFB1, VEGFA, and HAVCR2; CD44+ T cells express CD274, TGFB1, CTLA4, LAG3, and PDCD1." (PMID 35187044, 2021). "In our in vivo model, however, properdin-deficient mice, when inoculated with logarithmically growing B16F10 cells, showed decreased levels in blood of the chemoattractants C5a and CCL2 and in tumour of the mediators CCL2, CCL3, IL-13, and TIMP-1." (PMID 33494138, 2021).
tumor (continued). "Taken together, these results demonstrated that both IL-4 and IL-13 were upregulated in ILC2s of NSCLC patients, particularly in ILC2s derived from tumor tissues." (PMID 34194433, 2021). "In an acute promyelocytic leukemia model, elevated tumor-derived PGD2 and NKp30-B7H6 engagement was found to activate ILC2s, which in turn drove the activation of M-MDSCs via IL-13 secretion." (PMID 34884995, 2021). "On the contrary, M2 cells are activated by type II cytokines such as IL-4, IL-10, IL-13, and transforming growth factor (TGF)-β, performing a pro-tumor immune response by producing factors as STAT3, which contribute to tumor proliferation." (PMID 33917013, 2021). "While most studies suggest that diverse NKT cells inhibit anti-tumour immunity, iNKT cells contribute to natural tumour surveillance with immediate cytokine secretion (IFN-γ, TNF, IL-13, IL-17, IL-4, IL21, IL-22) and FasL/TRAIL pathways." (PMID 33499101, 2021). "Of the cytokines analysed, nine (CD30L, CCL11, CCL24, IGFBP5, IL-4, IL-13, MIP-3ß, CXCL4 and TPO) were significantly more abundant in 4T1 primary tumours than in 67NR primary tumours (Fig. 4aiii)." (PMID 33795809, 2021). "It was shown, that circulating monocytes or tissue residing macrophages are recruited and stimulated by different tumor-derived signals, such as chemo-attractants, e.g. CCL2 or cytokines, e.g. IL-4, IL-10 and IL-13." (PMID 34579743, 2021). "Regarding the functional molecules of ILC2s, PD-1high ILC2s in tumor tissues expressed much higher levels of IL4 and IL13 than did PD-1low ILC2s in terms of mRNA level." (PMID 34194433, 2021). "These tumor-infiltrating TAM are skewed toward CD163+ M2 phenotype under the action of the transcription factor, GATA3, and cytokines, including IL-4, IL-6, and IL-13, and promoted an immunosuppressive TME in EAC." (PMID 33995371, 2021). "TH2 cells are responsible for the increase in population of tumor infiltrating M2 macrophages and eosinophils in the TME, via their expression of IL-5 and IL-13, which regulate TGF-β secretion and immunosuppressive responses." (PMID 34012451, 2021). "Various cytokines, such as IL-13, IL-15, and IL-32, and surface proteins, including CD47, CD40, and CD28, provide the direct molecular bridge between tumor cells and adjacent cells, resulting in tumor progression." (PMID 34830466, 2021). "Th2 cytokines such as IL-4, IL-10, and IL-13 are able to induce M2 macrophages which have reduced cytotoxic activity and dampens CD8 T cell-mediated anti-tumor activity." (PMID 33117354, 2020). "Th2 cytokines such as IL-4, IL-10, IL-13, and Tgf-β that inhibit anti-tumor responses can also be released by myeloid derived suppressor cells (MDSC) that have been activated by tumor cells." (PMID 32508830, 2020). "Widespread cell death in breast cancer during postpartum involution triggers wound-healing cytokines, including IL-4, IL-13, and IL-10, in the TME to promote metastatic tumor progression." (PMID 32346605, 2020). "Concentrations of IL-2, IL-13 and CCL5 in the irradiated tumor were similarly decreased by DEX treatment." (PMID 32325715, 2020). "IL4R is composed of several distinct chains, on several tumor cells IL4Rα and IL13Rα’ chains are expressed and bind IL4, while in many solid tumor IL13 binds the chains IL-4Rα and IL13Rα1 and IL13Rα2." (PMID 32957689, 2020). "Because IL4, IL13, IL10, and CSF-1 are stimuli in M2 differentiation as reported in previous studies 6, 20, we performed qRT-PCR in FOXO1(+) and FOXO1(-) tumor cells to detect the expression of these genes." (PMID 33052231, 2020). "Only SFV4-infected tumor cells consistently induced DCs to secrete Th1 cytokines (IFN-γ, IL-12, TNF-α), Th2 cytokines (IL-4, IL-13), proinflammatory cytokines (IL-6, IL-8, IL-1β,) and anti-inflammatory cytokine (IL-10)." (PMID 31969562, 2020). "In tumors, IL-4, IL-13, IL-10, TGF-β, and CXCL5 increase tumor cell growth and metastasis through efferocytosis-induced cell clearance and macrophage polarization in the TME." (PMID 32346605, 2020).